RPL29P4 (ribosomal protein L29 pseudogene 4)
Synonyms: bA632C17A.1; formerly RPL29P3
Gene: Processed pseudogene on chromosome 6 (117,998,975 to 117,999,448, forward strand). Ensembl gene ENSG00000230202.
Diseases named in the same sentence as RPL29P4 in open-access papers:
RPL29P4 is named in the same sentence as 1 disease in open-access papers, as found by Europe PMC text mining. Sharing a sentence is not in itself a finding about the gene and the disease. The quoted sentences say what the papers report.
adenoma (1 paper, 2025). A neoplasm arising from the epithelium. "Interestingly, non-coding RNAs, such as LOC107984755 and RPL29P4, were upregulated, reflecting a shift towards altered cellular regulation as the adenomas became more advanced." (PMID 40003985, 2025).